RN7SL78P (RNA, 7SL, cytoplasmic 78, pseudogene)
Gene: Miscellaneous RNA gene on chromosome 10 (87,832,818 to 87,833,098, reverse strand). Ensembl gene ENSG00000243782.
Homologues: Orthologues: chimpanzee Metazoa_SRP (99% identical), macaque Metazoa_SRP (90% identical). Paralogues in human: RN7SL1 (81% identical), RN7SL2 (81% identical), RN7SL444P (80% identical), RN7SL3 (79% identical), RN7SL630P (79% identical), RN7SL220P (78% identical), RN7SL478P (78% identical), RN7SL543P (78% identical), RN7SL709P (78% identical), RN7SL296P (78% identical), RN7SL814P (78% identical), RN7SL865P (78% identical), and 706 more.